MELK (maternal embryonic leucine zipper kinase)
Diseases named in the same sentence as MELK in open-access papers (continued):
Sharing a sentence is not in itself a finding about the gene and the disease.
melanoma (continued). "MELK knockdown lead to sharply reduce invasive and metastatic capacity in melanoma and lung cancer." (PMID 33962400, 2021). "Indeed, MELK is overexpressed in primary and even more in metastatic melanoma, suggesting its implications in melanoma progression." (PMID 33431809, 2021). "However, MELK has been reported to support growth in several other cancer types, including colorectal cancer and melanoma." (PMID 29417930, 2018). "Importantly, MELK expression correlates with melanoma progression." (PMID 33431809, 2021). "To examine the role of MELK in other cancer types, we used CRISPR/Cas9 to generate multiple MELK-knockout (MELK-KO) clones in A375, a melanoma cell line, and DLD1, a colorectal cancer cell line." (PMID 29417930, 2018). "In this context, it could be interesting to study the effect of the combination of CRO15 or other MELK inhibitors and BRAF inhibitors for melanoma treatment." (PMID 33431809, 2021). "This set of genes included forkhead box C1 (FOXC1), keratin 14 (KRT14), cyclin E1 (CCNE1), melanoma inhibitory activity (MIA) and secreted frizzled-related protein 1 (SFRP1), while expression of CDCA1 and MELK, (neither of which were detectable in MCF7), did not change following SOX11 depletion." (PMID 26894864, 2016).
colorectal cancer (16 papers, 2015 to 2025). A primary or metastatic malignant neoplasm that affects the colon or rectum. "It has been reported that MELK was associated with increased resistance of colorectal cancer cells against radiation and 5-FU, sanguinarine mightbe a candidate therapy for apoptosis resistant patients." (PMID 29783958, 2018). "Recently, MELK has been defined as a crucial oncogene that plays indispensable roles in the Akt/mTOR signaling pathway to mediate the progression of colorectal cancer (CRC)." (PMID 37340189, 2023). "For example, lncRNA LINC02418 can serve a value in the diagnosis of colorectal cancer by regulating MELK expression and acting as a ceRNA31." (PMID 32826862, 2020). "MELK knockdown decreased proliferation and anchorage-independent growth in vitro, and decreased tumor growth in vivo in breast, pancreatic, and colorectal carcinomas." (PMID 25852826, 2015). "In colorectal carcinoma, MELK expression was elevated when compared to normal tissues, and was found to be spontaneously elevated in a murine model of intestinal tumorigenesis." (PMID 25852826, 2015). "A recent study demonstrated that MELK can be upregulated by LINC02418 in colorectal cancer." (PMID 32190687, 2020). "Additionally, in multipotent neural progenitors (MNPs), MELK is considered to be a marker of self-renewal and MELK depletion sensitizes colorectal cancer cells to radiation or 5-FU treatment." (PMID 28235006, 2017). "Both authors reported an active role for this lncRNA in tumorigenesis and in a CRC (colorectal cancer) model, and interestingly, Zhao demonstrated that LINC02418 upregulated maternal embryonic leucine zipper kinase (MELK) expression by acting as a ceRNA, which absorbs miR-1273g-3p." (PMID 33672425, 2021).
lung carcinoma (14 papers, 2012 to 2025). "Furthermore, MELK is highly expressed in multiple human cancers, including prostate, gastric, and lung cancer, and is significantly associated with the poor overall survival of cancer patients." (PMID 31358735, 2019). "In accordance with previous literatures concerning MELK in NSCLC, we found that MELK was up-regulated in NSCLC tumor samples compared with normal specimens by analyzing the lung carcinoma mRNA microarray profile from the GEO datasets." (PMID 33931086, 2021). "In this study, bioinformatics analysis showed that MELK was highly expressed in lung cancer and negatively correlated to the survival of lung adenocarcinoma (LUAD)." (PMID 33262323, 2020). "Increased MELK expression has been identified in multiple human cancers: prostate, breast, brain, colorectal, gastric and lung cancer." (PMID 29783958, 2018). "To further validate the MELK-specific in vivo tumor suppressive effect, we examined PC-14 lung cancer cells in which MELK expression was hardly detectable." (PMID 23283305, 2012). "Moreover, MELK exhibits high expression levels in lung cancer and is negatively correlated with the survival of LUAD patients." (PMID 39940833, 2025). "Additionally, MELK has been characterized as an oncogenic kinase essential for metastasis and mitotic progression in lung carcinoma." (PMID 40699665, 2025). "Moreover, patients with high MELK expression showed a significantly decreased overall survival compared to that with low MELK expression in lung cancer by Kaplan−Meier Plotter." (PMID 33931086, 2021). "In addition, MELK was highly expressed in three types of lung cancers including LUAD, LUSC, and LULC." (PMID 33262323, 2020). "To explore whether MELK is a novel drug target for lung cancer, we checked the expression of MELK in patients with lung cancer and investigated its roles in the migration, invasion, and growth in lung cancer cells and nude mice." (PMID 33262323, 2020). "Notably, the overexpression of MELK promoted the migration and invasion of lung cancer cells." (PMID 33262323, 2020). "Emerging evidence has shown that abnormal expression of MELK might be involved in the tumorigenesis and progression of human cancers, such as prostate, breast, ovarian, oesophageal, gastrointestinal tract, and lung cancers, including chemotherapy resistance, stem cell renewal, and tumour growth." (PMID 33962400, 2021). "Furthermore, the effects of OTSSP167 on cell viability, LDH release, apoptosis, morphology and related proteins were almost eliminated by Emricasan, a pan-inhibitor of caspase, suggesting that inhibition of MELK may induced the apoptosis-mediated pyroptosis of lung cancer." (PMID 33262323, 2020). "Our result suggests that MELK may be a pan-cancer oncogenic kinase and a promising selective therapeutic target for multiple cancer types including uterine corpus endometrial carcinoma, bladder urothelial carcinoma, lung cancer, liver cancer, and kidney cancers." (PMID 28489584, 2017).
triple-negative breast carcinoma (13 papers, 2017 to 2025). An invasive breast carcinoma which is negative for expression of estrogen receptor (ER), progesterone receptor (PR), and human epidermal growth factor receptor 2 (HER2). "Previously, we established that triple-negative breast cancer cell lines harboring CRISPR/Cas9-induced null mutations in MELK proliferate at wild-type levels in vitro." (PMID 29417930, 2018). "In contrast to these results, we recently reported that triple-negative breast cancer cells harboring CRISPR/Cas9-induced loss-of-function mutations in MELK proliferate at wild-type levels in vitro." (PMID 29417930, 2018). "Studies have indicated that MELK is associated with metastasis in triple-negative breast cancer." (PMID 38382096, 2024). "Maternal embryonic leucine zipper kinase (MELK) has emerged as a potential driver of progression and metastasis of various cancers, including triple-negative breast cancer (TNBC)." (PMID 40076867, 2025). "Our study demonstrates that maternal embryonic leucine zipper kinase (MELK) plays a critical role in the aggressive behavior of triple-negative breast cancer (TNBC)." (PMID 40076867, 2025). "Studies have shown that MELK is a novel biomarker and a potential therapeutic target in cervical cancer, triple-negative breast cancer and gastric cancer." (PMID 31788359, 2019). "Our previous work demonstrated that MELK is dispensable for the proliferation of triple-negative breast cancer cells in vitro." (PMID 29417930, 2018). "In triple-negative breast cancer models, KLT effectively blocked cell cycle progression at the G2/M phase by downregulating CDK1, CDK2, and CHEK1, inhibiting CDC25A, CDC25B, MELK, and AURKA activity, suppressing mitosis, and inducing apoptosis." (PMID 41164166, 2025). "We previously showed that MELK was not required for cell division in two triple-negative breast cancer cell lines, Cal51 and MDA-MB-231." (PMID 29417930, 2018). "We conclude that these seven triple-negative breast cancer cell lines are not dependent on MELK for cell fitness." (PMID 28337968, 2017). "We conclude that MELK is not an absolute requirement for triple-negative breast cancer proliferation, and that OTS167 blocks growth in a MELK-independent manner." (PMID 28337968, 2017). "However, it has been reported that MELK is not required in triple-negative breast cancer (TNBC) and other cancer types." (PMID 33520717, 2020).
gastric cancer (12 papers, 2014 to 2022). A primary or metastatic malignant neoplasm involving the stomach. "MELK mRNA and protein expression were both elevated in human gastric cancer, and this was associated with chemoresistance to 5-fluorouracil (5-FU)." (PMID 24885567, 2014). "This enhanced expression of MELK is shown to be associated with pleiotropic effects in gastric cancer cells, including increased cell proliferation, migration, and invasion." (PMID 24885567, 2014). "Overexpression of MELK, a serine/threonine kinase implicated in embryogenesis and cell cycle control has been identified in numerous human cancer types including breast, prostate, brain, colorectal and gastric cancer." (PMID 28122328, 2017). "MELK knockdown or deletion in GC (gastric cancer) and ovarian cancer cells activates G2/M arrest and enhances apoptosis." (PMID 29100313, 2017). "We also analyzed the correlation between MELK expression and clinicopathological parameters and found that MELK protein expression was higher in well differentiated and intestinal type gastric cancers." (PMID 24885567, 2014). "In agreement with this earlier work, we found that MELK had wide-spread effects involving chemoresistance, cell proliferation, migration, invasion and cytoskeleton regulation in gastric cancer cells." (PMID 24885567, 2014). "MELK expression levels in human gastric cancer were determined by quantitative-PCR and immunohistochemistry." (PMID 24885567, 2014). "Together, these data clearly indicate that MELK is overexpressed in gastric cancer tissues and cell lines." (PMID 24885567, 2014). "We also found that MELK mRNA and protein were elevated in gastric cancer cell lines compared with the immortalized normal gastric epithelial cell line GES-1." (PMID 24885567, 2014). "Although MELK has been the focus of many cancer-related studies, most of these lacked data related to the protein level, and few have investigated gastric cancer." (PMID 24885567, 2014). "Knockdown of MELK significantly suppressed cell proliferation, migration and invasion of gastric cancer both in vitro and in vivo, decreased the percentages of cells in the G1/G0 phase and increased those in the G2/M and S phases." (PMID 24885567, 2014). "In recent years, many studies have shown that MELK is upregulated in multiple types of human tumors including lung, breast, and gastric cancers, the effect of RNAi-mediated MELK knockout has confirmed that MELK expression is essential for the proliferation and invasion of cancer cells." (PMID 35440604, 2022). "In addition, inhibition of MELK resulted in suppression of migration, invasion and metastasis in gastric cancer." (PMID 32047721, 2020). "Indeed, ectopic expression of MELK drastically promoted gastric cancer cell proliferation, migration and invasion in vitro and accelerated tumor growth and peritoneal spreading and metastasis in nude mice." (PMID 32047721, 2020). "Likewise, a larger portion of advanced GC patient tissues expressed MELK compared to early gastric carcinoma tissues (T1 vs. T2-4, p=0.004), and expression tended to increase in more advanced TNM stages (p=0.056)." (PMID 26701722, 2016). "As chemoresistance is closely correlated with CSCs and MELK is generally regarded as a marker of CSCs, we propose that MELK expression might be elevated in gastric CSCs and is closely related to chemoresistance in gastric cancer." (PMID 24885567, 2014). "In summary, our data indicate that MELK expression is elevated in gastric cancer." (PMID 24885567, 2014). "Thus, together, these results implicate MELK in the regulation of characteristic cellular behaviors found in gastric cancers." (PMID 24885567, 2014). "This study is aimed to investigate the mechanisms of MELK-mediated development of gastric cancer." (PMID 24885567, 2014). "The presence of MELK was elevated in well differentiated and intestinal type gastric cancer." (PMID 24885567, 2014).
gastric cancer (continued). "We characterized the expression of MELK in gastric cancer (GC) and measured the effects of reducing MELK mRNA levels and protein activity on GC growth." (PMID 26701722, 2016). "MELK may be a potential target for treatment against gastric cancer." (PMID 24885567, 2014). "This might be due to the already relative high expression of MELK in gastric cancer." (PMID 24885567, 2014). "MELK promotes cell migration and invasion via the FAK/Paxillin pathway, and plays an important role in the occurrence and development of gastric cancer." (PMID 24885567, 2014). "We evaluated the expression of MELK mRNA in 150 pairs of gastric cancer and non-tumor tissues by qPCR." (PMID 24885567, 2014). "We found higher expression levels of MELK mRNA in these gastric cancer tissues compared to non-tumor tissues." (PMID 24885567, 2014). "Next we investigated the MELK protein levels in the human gastric cancer and non-tumor tissues by IHC." (PMID 24885567, 2014). "Furthermore, MELK was found to promote cell migration and invasion via the FAK/Paxillin pathway, which could thus be a potential focus of future therapy against gastric cancer." (PMID 24885567, 2014). "We performed Quantitative Real-time PCR (qPCR) on 6 up-regulated genes (COL1A, BGN, SPP1, MELK, IGFBP4, SPARC) and 4 down-regulated genes (PGC, SST, MT1X, S100P) to verify our data in gastric cancer tissues (Tumor) and noncancerous tissues (Normal)." (PMID 25928635, 2015).
cervical carcinoma (10 papers, 2018 to 2023). A carcinoma arising from either the exocervical squamous epithelium or the endocervical glandular epithelium. "MELK is a potential therapeutic target for cervical cancer and its high expression is associated with poor prognosis in adrenocortical carcinoma." (PMID 34097054, 2021). "In this report, knockdown of MELK transfected with siRNA caused DNA damage of cervical cancer cells." (PMID 30334367, 2018). "Our research reveals that MELK plays a vital role in the proliferation of cervical cancer cells and provides new targets for developing drugs and diagnostic markers for the treatment of cervical cancer." (PMID 34671205, 2021). "However, higher MELK expression was significantly associated with cervical cancer metastasis in the study." (PMID 30334367, 2018). "To further reveal the role of MELK in the mitosis of Hela cervical cancer cells, we performed a bioinformatics analysis of the MELK interactome." (PMID 34671205, 2021). "The candidate genes SPP1, FOXM1, LYN, COL6A3, CCL21, TTK and MELK at mRNA level, emerge as promising candidate markers for cervical cancer prognosis and also emerge as potential therapeutic drug targets." (PMID 33829064, 2021). "We also collected cervical tissues and detected MELK expression in paraffin sections of cervical cancer samples and their adjacent normal samples." (PMID 34671205, 2021). "We used the different concentrations of MELK-8A in cervical cancer cells (HeLa, CaSki, and C33a) and found that the greater the inhibitor concentration, the lower the cell proliferation ability in a dose-dependent manner." (PMID 34671205, 2021). "In this study, we investigated the role of MELK (maternal embryonic leucine zipper kinase) in cervical cancer." (PMID 34671205, 2021). "We found that MELK is a survival kinase for cervical cancer cells, and MELK inhibition blocked the growth of cervical cancer cells." (PMID 34671205, 2021). "MELK mRNA is more highly expressed in cervical cancer tissues than normal cervical tissue, and MELK expression increased in cervical cancers from grade 1 to grade 3." (PMID 34671205, 2021). "The TCGA tumor database analysis found that the MELK RNA level in cervical cancer tissue was significantly higher than other tumor tissues." (PMID 34671205, 2021). "In vitro and in vivo experiments have shown that MELK targeted specific shRNA has a significant inhibitory effect on the growth of cervical cancer cells." (PMID 34671205, 2021). "To reveal the role of MELK in the process of cervical cancer cell division, we tried to identify the proteins of co-localization and interaction with MELK protein and explore the potential biological functions of MELK." (PMID 34671205, 2021). "According to the TCGA data, we verified by immunohistochemistry that the expression of MELK in cervical cancer tissues was indeed higher than that in adjacent tissues." (PMID 34671205, 2021). "To define that MELK plays a vital role in the progression of human cervical cancer, we first analyzed the expression of MELK in previously published gene expression datasets of patient-derived cervical cancer samples." (PMID 34671205, 2021). "Our study also indicates that pharmacological inhibition of MELK with MELK inhibitor can exert strong inhibitory effects on tumor growth in various cervical cancer types, including cervical adenocarcinoma or squamous cell carcinoma." (PMID 34671205, 2021). "Our results showed that MELK knockdown significantly inhibited the proliferation of cervical cancer cells (HeLa and CaSki)." (PMID 34671205, 2021). "Previous studies demonstrated that highly expressed MELK correlated with the histopathological grading and tumor metastasis in patients with cervical cancer." (PMID 32047721, 2020). "MELK was highly expressed in clinical specimens of cervical cancer patients and the high expression rate was 56.92%." (PMID 30334367, 2018).